IL17REL (interleukin 17 receptor E like)
Synonyms: FLJ41993
Tractability: Antibody: UniProt places it where antibodies can reach, with medium confidence; UniProt predicts a signal peptide or a membrane-spanning region; its Gene Ontology location is reachable by antibodies, with medium confidence.
Gene: Protein-coding gene on chromosome 22 (49,991,811 to 50,012,765, reverse strand). Ensembl gene ENSG00000188263.
Subcellular location: Secreted
Gene Ontology:
Molecular function: interleukin-17 receptor activity
Biological process: interleukin-17-mediated signaling pathway; positive regulation of cytokine production involved in inflammatory response
Cellular component: plasma membrane; extracellular region
Genetic constraint (gnomAD): Loss-of-function variants: 36 observed, 41.65 expected, observed/expected ratio (o/e) 0.86, 90% interval 0.66 to 1.14. The upper end of that interval is the gene's LOEUF score, 1.14, which puts it in group 5 of 6, group 1 being the genes least tolerant of losing a copy. Missense variants: 467 observed, 418.27 expected, observed/expected ratio (o/e) 1.12, 90% interval 1.03 to 1.21. Synonymous variants: 204 observed, 176.29 expected, observed/expected ratio (o/e) 1.16, 90% interval 1.03 to 1.3.
Homologues: Orthologues: macaque IL17REL (64% identical), dog IL17REL (61% identical), chimpanzee IL17REL (60% identical), tropical clawed frog il17rel (33% identical), zebrafish il17rel (32% identical).
Diseases named in the same sentence as IL17REL in open-access papers:
IL17REL is named in the same sentence as 12 diseases in open-access papers, as found by Europe PMC text mining. Sharing a sentence is not in itself a finding about the gene and the disease. The quoted sentences say what the papers report.
ulcerative colitis (4 papers, 2013 to 2023). An inflammatory bowel disease involving the mucosal surface of the large intestine and rectum. "Though IL17REL was found to be highly associated with gout and ulcerative colitis in genome-wide association studies (GWAS), the expression and function of IL17REL in different cell types remain largely unknown, especially in human cancers." (PMID 37111458, 2023). "However, in the chronic enteritis comparison, IL17REL is the largest (by magnitude) down-regulated gene given PM diet treatment for 12-weeks, a gene which has been strongly associated to human ulcerative colitis." (PMID 28723948, 2017). "Interestingly, a genome-wide association study and later whole-exome sequence analysis identified IL17REL as a major risk locus in humans for ulcerative colitis, and expression of IL-17 has been implicated in ulcerative colitis / inflammatory bowel disease and celiac disease." (PMID 28723948, 2017). "The region around the LOD score peak for RANTES (22q13) contains the gene IL17REL (IL17 Receptor E Like), which was recently identified in a genome-wide association study (GWAS) for ulcerative colitis." (PMID 23936524, 2013).
inflammatory bowel disease (3 papers, 2016 to 2024). A spectrum of small and large bowel inflammatory diseases of unknown etiology. "Variants in IL17REL have been implicated in inflammatory bowel disease though the relations between variation in IL17REL and cardiac function are unclear." (PMID 27589061, 2016). "In genome-wide association (GWAS) studies and whole exon sequencing studies, IL17REL was found to be strongly correlated with the development of inflammatory bowel disease (IBD)." (PMID 38900244, 2024).
colitis (1 paper, 2017). Inflammation of the colon. "Although IL17RE has been reported to be a functional receptor for IL17C as well as mediating the mucosal immunity in the small intestine of mice during acute experimental colitis, the overall function of IL17REL still remains unclear." (PMID 28886140, 2017).
enteritis (1 paper, 2017). Inflammation of the small intestine. "We also identified a transcript (C172972_c0_seq1) for interleukin-17 receptor E-like (IL17REL) from the enteritis comparison group as the most down-regulated gene in the comparison." (PMID 28723948, 2017).
tumor (2 papers, 2023 to 2024). "Moreover, we also find that two genes encoding IL17 receptor family members, IL17RB and IL17REL, are associated with improved prognosis and may modulate the anti-tumor activity of memory B, NK cells, and T cell subsets in HPV-infected HNSCC patients." (PMID 37111458, 2023). "We have uncovered a novel association between a higher tumor expression of IL17RB with CD4 Tem, memory B, and activated NK TS and IL17REL with CD8 Tcm, memory B, M1 macrophages and T Helper cell TS and the improved prognosis of HPV-infected HNSCC patients." (PMID 37111458, 2023). "Analysis of secretome transcripts and cognate receptors revealed that tumor expression of IL17RB and IL17REL are associated with a higher viral load and memory B and activated NK cell TS, as well as improved prognosis in HPV-infected HNSCC patients." (PMID 37111458, 2023).
cancer (1 paper, 2023). A tumor composed of atypical neoplastic, often pleomorphic cells that invade other tissues. "The IL17 signaling pathway has previously been found to be associated with poor prognosis in cancers, whilst the role of IL17REL in cancers remains unknown." (PMID 37111458, 2023).
IL17REL also shares sentences with these, for which no sentence is quoted: atrial fibrillation (1 paper); cardiac arrhythmia (1); celiac disease (1); gout (1); head and neck squamous cell carcinoma (1); skin melanoma (1).